UBD (ubiquitin like modifier D)
Diseases named in the same sentence as UBD in open-access papers (continued):
Sharing a sentence is not in itself a finding about the gene and the disease.
cholestasis (1 paper, 2026). Impairment of the bile flow caused by obstruction within the liver, or outside the liver in the bile duct system. "Collectively, these results demonstrate that increased hepatic UBD expression is associated with enhanced T cell infiltration in the livers of cholestasis." (PMID 41399364, 2026). "To investigate the potential functions of UBD in cholestasis, we stratified cholestasis samples from three datasets into UBD low- and high-expression groups based on median UBD levels." (PMID 41399364, 2026). "In summary, our study identified UBD as a key gene that correlated with both cholestasis severity and hepatic T cell infiltration." (PMID 41399364, 2026). "Secondly, the potential utility of UBD as a circulating biomarker for cholestasis remains to be validated through systematic analysis of serum UBD levels in patient cohorts." (PMID 41399364, 2026). "This work aimed to reveal the potential role of UBD in the progression of cholestatic liver disease, which may provide novel therapeutic targets for patients with cholestasis." (PMID 41399364, 2026).
colorectal adenocarcinoma (1 paper, 2025). The most common type of colorectal carcinoma. "After evaluating the expression levels of UBD in tumors with varying microsatellite instability (MSI) statuses, it was found that UBD expression was significantly associated only with the MSI status in colorectal adenocarcinoma (COAD)." (PMID 41347086, 2025).
colorectal tumors (1 paper, 2021). "In vivo experiments also confirmed that the growth of colorectal tumors was suppressed when UBD was knocked down." (PMID 34350116, 2021).
esophageal cancer (1 paper, 2025). A primary or metastatic malignant neoplasm involving the esophagus. "Previous results indicated that esophageal cancer patients with high UBD expression had poorer prognoses, prompting us to further explore the biological functions of UBD in esophageal cancer." (PMID 41347086, 2025). "Additionally, we partially revealed the relationship between UBD and the malignant phenotype of esophageal cancer for the first time using overexpressed esophageal cancer cell lines and transcriptomic sequencing." (PMID 41347086, 2025).
Hyperglycemia (1 paper, 2024). An increased concentration of glucose in the blood. "The current study found that PKCε was upregulated in small nociceptors under hyperglycemia and was highly colocalized with IRE1α and UBD; these molecules are involved in the ERAD and UPS systems, respectively." (PMID 37906389, 2024).
leprosy (1 paper, 2015). Leprosy is a chronic infectious disease affecting primarily the skin and peripheral nervous system. "The UBD gene was found to be highly expressed in leprosy, indicating that the ubiquitination is a common process across the spectrum of the disease, but with higher values in type 1 reaction (Figure 3O1 and Supplement 19)." (PMID 26635870, 2015).
lymph node metastasis (1 paper, 2021). "A previous study shows that UBD expression is highly upregulated in CRC tissues, and is closely associated with clinical staging and lymph node metastasis of patients with CRC, but not related to tumor size or tumor differentiation." (PMID 34350116, 2021).
metastatic tumors (1 paper, 2026). "Elevated UBD expression in primary and metastatic tumors is associated with aggressive clinicopathological features, suggesting that its assessment could help identify patients at increased risk of distant relapse." (PMID 41583390, 2026).
pulpitis (1 paper, 2021). Inflammation of the dental pulp. "For the first example, UBD (Ubiquitin D) was shown to have multiple cellular processes that occurred in pulpitis: regulating NF-kappa B signaling pathway, mediating cell apoptosis in a caspase-dependent manner, and being involved in the maturation of dendritic cells." (PMID 33777260, 2021).
rectal cancer (1 paper, 2023). A primary or metastatic malignant neoplasm that affects the rectum. "Interestingly, in line with this finding, it has been reported that increased UBD levels in rectal cancer correspond to favorable treatment outcomes." (PMID 38136595, 2023).
cancer (58 papers, 2006 to 2026). A tumor composed of atypical neoplastic, often pleomorphic cells that invade other tissues. "In most cancer types, the methylation levels of UBD across different DNA methylation regions are downregulated in tumors." (PMID 41347086, 2025). "When samples were divided into high and low UBD expression groups based on the median value, the results showed that two drugs (imatinib and TTNPB) had therapeutic potential in the high UBD expression group across more than 20 cancer types." (PMID 41347086, 2025). "Our findings demonstrate that UBD is aberrantly expressed in a cancer-specific manner, with significant upregulation in gastrointestinal and hepatic cancers, contrasting with downregulation in THCA and KICH." (PMID 41347086, 2025). "The inconsistent prognostic role of UBD—protective in cancers like SKCM and SARC but risky in UVM and PAAD—likely arises from its context-dependent functions within distinct TMEs." (PMID 41347086, 2025). "These proteins exhibited significant positive correlations with UBD mRNA expression across more than five cancer types." (PMID 41347086, 2025). "Our results not only delineate UBD as a potential biomarker for tumors with IFN-γ Dominant(C2)immune subtype but also highlight its therapeutic potential in cancers." (PMID 41347086, 2025). "“FAT10 cancer signalling” with the higher expression of UBD (FAT10) predicted to promote carcinogenesis via NF-κB and TGFB is illustrated." (PMID 35061738, 2022). "The results showed that UBD expression was clearly increased and was mainly located in the nucleus of cancer cells." (PMID 34350116, 2021). "The other major pathways identified in terms of regulated gene numbers were HOX antisense intergenic RNA) regulatory pathway (HOTAIR) and HLA-F adjacent transcript 10, also known as UBD) cancer signaling pathway (FAT10)." (PMID 34946170, 2021). "UBD is a small ULM in the ubiquitin–proteasome system that contributes to cancer progression." (PMID 41583390, 2026). "Notably, previous research demonstrated that UBD can stabilize or degrade substrates in various cancer cells." (PMID 41583390, 2026). "We further validate key findings using in vitro models to elucidate UBD’s role in cancer cell." (PMID 41347086, 2025). "Thus, UBD’s dual impact reflects a balance between its pro-apoptotic versus oncogenic degradation roles, dictated by the immune and molecular context of each cancer." (PMID 41347086, 2025). "Given the widespread role of UBD in other cancers, its potential application in other tumor types may provide additional avenues for precision cancer immunotherapy." (PMID 40692714, 2025). "High UBD expression may facilitate metabolic reprogramming in cancer cells by regulating the expression of these glycolysis‐related proteins, thereby enhancing the metabolic activity and therapeutic resistance of OC." (PMID 40692714, 2025). "In summary, this study reveals that UBD is aberrantly expressed across multiple cancer types and may serve as a potential prognostic biomarker." (PMID 41347086, 2025). "Based on these results, we hypothesize that UBD may facilitate cancer cell metabolic reprogramming by modulating key steps of glycolysis, thereby providing energy support for tumor cell growth and immune evasion." (PMID 40692714, 2025). "Furthermore, researches have shown that UBD is frequently overexpressed in multiple types of cancers, and abnormal expression and dysfunction of UBD are closely associated with the occurrence and development of tumors." (PMID 34350116, 2021). "In addition, there were multiple genes induced that are involved with cell and organelle structure and function (PNCK, UBD, CDH2, HERC5) and importantly, genes associated with the prostate, AR (MMP7, CDH2, ENO2, IGFBP3) and cancer (IFIT3, IFI44L)." (PMID 29416764, 2018).
cancer (continued). "Collectively, these data indicate that UBD may be a marker for precancerous lesions and may promote cancer progression." (PMID 20808312, 2010). "Additionally, exploring UBD’s synergy with immune checkpoint inhibitors in C2-subtype cancers could unveil strategies to enhance immunotherapy responsiveness." (PMID 41347086, 2025). "Additionally, the expression of SLC2A3, a key glucose transporter in glycolysis, was markedly increased, indicating that UBD overexpression may facilitate glycolytic metabolism by enhancing glucose uptake in cancer cells." (PMID 40692714, 2025). "Importantly, while many of the genes affected by epigenetic priming are not necessarily cancer drivers, in the case of hypomethylated/upregulated genes such as UBD and CREB5, these genes have been linked to prognosis and disease outcome." (PMID 34863035, 2022). "TNF-α expression was observed to upregulate expression of several cancer-associated genes in the epithelial cells which include extracellular matrix (ECM) remodeling genes such as MMP9, PLAU, FN1 and ICAM1, chemokines such as CCL2, CXCL2, CXCL3 and CXCL10 and regulatory genes such as UBD and PTGS2." (PMID 34946170, 2021). "Among UPS components, ubiquitin-like modifiers (UBLs) have emerged as critical regulators of substrate specificity, with Ubiquitin D (UBD/FAT10) representing a unique cytokine-inducible UBL that bridges inflammation, immunity, and cancer." (PMID 41347086, 2025). "Our study evaluated the prognostic value of UBD expression for OS, DFI, DSS, and PFI across various cancers using a univariate Cox regression model." (PMID 41347086, 2025). "These are worthwhile to point out that CST1, CHI3L1, UBD, and INHBA genes were verified by the GEPIA in both COAD and READ cancer types while ASCL2 was verified only in COAD cancer type by the GEPIA." (PMID 35333898, 2022). "Furthermore, UBD-mediated regulation of NF-κB may be targeted for new cancer therapeutics." (PMID 36699607, 2022). "Using these techniques, we showed upregulation of ubiquitin D (UBD, also known as FAT10) levels in cancer cells (signal log ratio 1.9) when compared with normal colon epithelial tissue (paper in preparation)." (PMID 20808312, 2010). "In addition, FBXO9, but not UBD, was found to be downregulated in OV and positively correlated with DNA damage repair pathways, suggesting FBXO9 as a potential cancer suppressor, likely via facilitating DNA damage repair." (PMID 38136595, 2023).
tumor (42 papers, 2006 to 2026). "Consistent with previous studies, the high expression of UBD is not only associated with tumor cell proliferation and migration but also with metabolic reprogramming in tumors." (PMID 40692714, 2025). "Clinical features demonstrated that overexpressed UBD was positively associated with tumor size and TNM stage, which was consistent with previous studies." (PMID 34350116, 2021). "It is interesting that the patients of stage II and III disease and tumours with positive UBD expression were at greater risk for tumour recurrence." (PMID 20808312, 2010). "Besides, in vivo experiments further demonstrated that UBD overexpression counteracted the suppression of tumor growth caused by SPIB knockdown." (PMID 41583390, 2026). "As high UBD protein expression was significantly associated with tumor size, we speculated that UBD may function in CRC proliferation." (PMID 34350116, 2021). "H&E staining and IHC showed higher tumor cell density in the UBD overexpression group compared to the other 2 groups, with enhanced cell proliferation, as shown by Ki67 staining." (PMID 41583390, 2026). "Immunofluorescence and IHC assays further demonstrated that Ki67 and UBD expression levels were decreased in tumor tissues treated with UBD in vivo siRNA." (PMID 41583390, 2026). "Hematoxylin and eosin (H&E) staining indicated that UBD knockdown led to a reduction in tumor cell population while simultaneously enhancing apoptotic activity." (PMID 41583390, 2026). "Functional assays showed that UBD enhances cell proliferation, tumor sphere formation, and migration, whereas its knockdown markedly inhibited tumor growth and reduced lung metastases in vivo." (PMID 41583390, 2026). "Tumor volume and weight were significantly increased in the UBD overexpression group compared to the control group." (PMID 41583390, 2026). "UBD overexpression promotes tumor growth, while MMP3 knockdown inhibits both tumor growth and metastasis." (PMID 41583390, 2026). "In contrast to these studies, our innovation lies in elucidating the role of glycolytic metabolism in macrophage polarization through UBD, providing a new molecular mechanism for tumor immune evasion." (PMID 40692714, 2025). "Specifically, OC patients with high UBD expression showed a 1.6‐fold increase in the proportion of M2 macrophages in their tumor tissue compared to those with low UBD expression." (PMID 40692714, 2025). "In contrast, UBD knockdown not only reduces tumor metabolic activity but also improves CD8+ T cell infiltration in the TME, enhancing the therapeutic efficacy of PD‐L1 antibody treatment." (PMID 40692714, 2025). "Increasing evidence suggests that UBD plays a significant role in tumorigenesis and also influences tumor immune evasion by regulating metabolic pathways." (PMID 40692714, 2025). "Flow cytometry analysis of immune cell infiltration in the tumor tissue showed that UBD knockdown increased CD8+ T cell infiltration, and the proportion of CD8+ T cells further increased after treatment with anti‐PD‐L1 antibody." (PMID 40692714, 2025). "High UBD expression significantly promotes M2 macrophage polarization and glycolytic activity, thereby enhancing tumor immune evasion." (PMID 40692714, 2025). "In the TCGA cohort, analysis of paired tumor and adjacent normal tissues revealed that UBD was significantly overexpressed in 10 tumor types, while it remained significantly downregulated in THCA." (PMID 41347086, 2025). "Paradoxically, UBD overexpression also induces apoptosis in specific cellular contexts, suggesting a dual role contingent on tumor microenvironment (TME) dynamics." (PMID 41347086, 2025). "Tumor samples from the TCGA cohort (n = 9,104) were stratified into high and low UBD expression groups based on the median expression value of UBD." (PMID 41347086, 2025).
tumor (continued). "Studies have shown that UBD is overexpressed in CRC tumor tissue, and its overexpression is positively correlated with tumor size and TNM stage in CRC patients." (PMID 35812403, 2022). "Taken together, we concluded that UBD is frequently upregulated in human CRC and that UBD has a potential role as a tumor promoter in CRC." (PMID 34350116, 2021). "Among these genes, CX3CR1 and UBD can promote tumor metastasis and the epithelial to mesenchymal transition." (PMID 32208363, 2020). "This analysis revealed that miR-133b was significantly downregulated in CRC tumor samples, while UBD and lncRNA ENST00000535511 were significantly upregulated in CRC tumor samples." (PMID 28177879, 2017). "Increased UBD expression was signicantly correlated with depth of tumour invasion (pT stage), LNM (pN stage), distant metastasis (M stage,), histologic grade and advanced American Joint Committe on cancer (AJCC) stage." (PMID 20808312, 2010). "tumour UBD expression shows some tissue specificity, with transcriptional upregulation observed in liver, uterine cervix, ovarian, pancreatic, gastric and small intestine adenocarcinomas, but not in thyroid, prostate or kidney cancers." (PMID 20808312, 2010). "Multivariate analysis demonstrated that positive tumour UBD expression remained a signicant independent prognostic factor for increased disease recurrence and decreased survival." (PMID 20808312, 2010). "Our results revealed significant correlations between tumour UBD overexpression and clinical stage, pT, pN stage, distant metastasis and tumour histological grade." (PMID 20808312, 2010). "A subcutaneous tumor experiment was carried to further explore the function of UBD in vivo." (PMID 41583390, 2026). "Elevated UBD levels were significantly associated with advanced tumor–node–metastasis (TNM) staging (P = 0.023), increased Ki67 expression (P = 0.017), and distant metastasis (P = 0.038)." (PMID 41583390, 2026). "Notably, UBD exhibits dual molecular functions within tumor cells—serving both degradative and stabilizing roles." (PMID 41583390, 2026). "Furthermore, analysis of the GSE4552 dataset demonstrated that UBD and SPIB are both highly expressed in TNBC, with a statistically significant positive association between their expression levels in tumor tissues." (PMID 41583390, 2026). "Tumor size reduction induced by SPIB knockdown was effectively reversed by UBD overexpression." (PMID 41583390, 2026). "Similarly, tumor sphere formation assays indicated that UBD overexpression restored the reduction in tumor sphere size and number induced by SPIB knockdown." (PMID 41583390, 2026). "Additionally, immunohistochemical analysis of macrophage polarization revealed that UBD knockdown significantly increased the proportion of M1 macrophages and decreased the proportion of M2 macrophages in tumor tissues." (PMID 40692714, 2025). "In experiments conducted using an OC mouse model, we found that overexpression of UBD significantly enhanced the immunosuppressive nature of the tumor tissue, as evidenced by an increase in the proportion of M2 macrophages and a decrease in CD8+ T cell infiltration." (PMID 40692714, 2025). "Although previous studies have established the critical role of macrophage polarization in tumor immune responses, the specific mechanisms by which UBD regulates macrophage polarization through metabolic pathways to influence immune evasion remain unclear." (PMID 40692714, 2025). "In immunogenic tumors (e.g., SKCM), UBD upregulation is linked to the C2 (IFN-γ-dominant) immune subtype, characterized by CD8+ T cell infiltration and pro-apoptotic activity, promoting anti-tumor responses." (PMID 41347086, 2025). "IF assays further confirmed elevated UBD expression in ESCA tumor tissues." (PMID 41347086, 2025). "Whether UBD expressed in tumor cells also contributes to OC progression remains an important question that requires further exploration." (PMID 40692714, 2025).